CABLES2 (Cdk5 and Abl enzyme substrate 2)
Description:
Unknown. Probably involved in G1-S cell cycle transition.
Synonyms: Ik3-2; C20orf150; dJ908M14.2
Tractability: PROTAC: ubiquitination databases record sites on it.
Gene: Protein-coding gene on chromosome 20 (62,388,630 to 62,407,303, reverse strand). Ensembl gene ENSG00000149679.
Subcellular location (Human Protein Atlas): Nucleoli
Pathways (Reactome):
Hemostasis: Factors involved in megakaryocyte development and platelet production
Gene Ontology:
Biological process: regulation of cell cycle
Genetic constraint (gnomAD): Loss-of-function variants: 34 observed, 45.27 expected, observed/expected ratio (o/e) 0.75, 90% interval 0.57 to 1. The upper end of that interval is the gene's LOEUF score, 1, which puts it in group 4 of 6, group 1 being the genes least tolerant of losing a copy. Missense variants: 481 observed, 539.82 expected, observed/expected ratio (o/e) 0.89, 90% interval 0.83 to 0.96. Synonymous variants: 229 observed, 232.8 expected, observed/expected ratio (o/e) 0.98, 90% interval 0.88 to 1.1.
Homologues: Orthologues: macaque CABLES2 (99% identical), dog CABLES2 (90% identical), guinea pig CABLES2 (89% identical), mouse Cables2 (89% identical), pig CABLES2 (88% identical), rat Cables2 (83% identical), chimpanzee CABLES2 (80% identical), tropical clawed frog cables2 (61% identical), zebrafish cables2a (56% identical), zebrafish cables2b (56% identical), Drosophila melanogaster CG6191 (34% identical), Caenorhabditis elegans Y71F9B.6 (24% identical). Paralogues in human: CABLES1 (58% identical).
Diseases named in the same sentence as CABLES2 in open-access papers:
CABLES2 is named in the same sentence as 7 diseases in open-access papers, as found by Europe PMC text mining. Sharing a sentence is not in itself a finding about the gene and the disease. The quoted sentences say what the papers report.
colorectal cancer (2 papers, 2020). A primary or metastatic malignant neoplasm that affects the colon or rectum. "Interestingly, seven of the shared significant genes have been associated to colorectal cancers, including UTP23, GREM1, SCG5, SMAD7, CABLES2, LAMA5, and PREX1." (PMID 32245788, 2020).
colorectal tumor (1 paper, 2017). "Box plots of gene expression profiles for FADS2, COLCA2, COLC1, and CABLES2 expression by genotype (cis-eQTL) in colorectal tumor tissue (left column)." (PMID 28506205, 2017). "Perhaps, the high frequency of copy number alterations at the CABLES2 gene observed in colorectal tumors contributes to the poor correlation with the cis-eQTL in tumor and normal tissue." (PMID 28506205, 2017). "Box plots of colorectal tumor versus normal tissue gene expression profiles for FADS2, COLCA2, COLC1, and CABLES2 (right column)." (PMID 28506205, 2017). "However, it was not a significant cis-eQTL in colorectal tumor tissue for the CABLES2 (p = 0.45) gene." (PMID 28506205, 2017).
gastric cancer (1 paper, 2026). A primary or metastatic malignant neoplasm involving the stomach. "The two loci (DOCK10 and FCN1-FCN2) replicated from CoGaPro1, and the 11 loci replicated from CoGaPro2 (CDK15, CROCC2-SNED1, TLR2-RNF175-SFRP2, WWC2, RELN, ZMYM5-ZMYM2, KLF12, SKAP1, CABLES2, and MIR630) gave further support for these genes being associated with a risk of CRC and gastric cancer." (PMID 41516419, 2026).
rectal cancer (1 paper, 2023). A primary or metastatic malignant neoplasm that affects the rectum. "Lastly, cg25415966 is located in CABLES2 which shows differential methylation in cancer and was included in a DNA methylation-based prognostic biomarker in rectal cancer." (PMID 37528416, 2023).
tumor (2 papers, 2017 to 2025). "Recent studies investigating gene expression have found that CABLES2 is a tumour suppressor involved in the apoptosis pathway and plays an important role in CRC carcinogenesis." (PMID 40506516, 2025).
CABLES2 also shares sentences with these, for which no sentence is quoted: cancer (1 paper); non-small cell lung carcinoma (1).